FRRS1 (ferric chelate reductase 1)
Description:
Ferric reductase that reduces Fe(3+) to Fe(2+) and could play a role in iron import into cells (By similarity). The electron donor and therefore the reaction mechanism are not known (By similarity).
Synonyms: SDFR2; SDR2
Tractability: Antibody: UniProt predicts a signal peptide or a membrane-spanning region. PROTAC: ubiquitination databases record sites on it; its protein half-life has been measured.
Gene: Protein-coding gene on chromosome 1 (99,703,970 to 99,766,635, reverse strand). Ensembl gene ENSG00000156869.
Subcellular location: Membrane
Gene Ontology:
Molecular function: oxidoreductase activity, acting on metal ions; oxidoreductase activity
Biological process: intracellular iron ion homeostasis
Cellular component: membrane
Genetic constraint (gnomAD): Loss-of-function variants: 20 observed, 26.99 expected, observed/expected ratio (o/e) 0.74, 90% interval 0.52 to 1.08. The upper end of that interval is the gene's LOEUF score, 1.08, which puts it in group 4 of 6, group 1 being the genes least tolerant of losing a copy. Missense variants: 333 observed, 394.04 expected, observed/expected ratio (o/e) 0.85, 90% interval 0.77 to 0.93. Synonymous variants: 114 observed, 134.81 expected, observed/expected ratio (o/e) 0.85, 90% interval 0.73 to 0.99.
Homologues: Orthologues: macaque FRRS1 (97% identical), chimpanzee FRRS1 (91% identical), rabbit FRRS1 (84% identical), dog FRRS1 (83% identical), pig FRRS1 (82% identical), guinea pig FRRS1 (80% identical), rat Frrs1 (79% identical), mouse Frrs1 (78% identical), tropical clawed frog frrs1 (57% identical), zebrafish frrs1b (44% identical), zebrafish frrs1a (43% identical), Drosophila melanogaster CG8399 (27% identical), and 7 more. Paralogues in human: REELD1 (18% identical), FRRS1L (12% identical).
Diseases named in the same sentence as FRRS1 in open-access papers:
FRRS1 is named in the same sentence as 5 diseases in open-access papers, as found by Europe PMC text mining. Sharing a sentence is not in itself a finding about the gene and the disease. The quoted sentences say what the papers report.
asthma (1 paper, 2023). "Asthma and AR share eight common genes (CLC, EMR4P, IL5RA, FRRS1, HRH4, SLC29A1, SIGLEC8, IL1RL1) that are presumed to describe the link for multimorbidity." (PMID 36825519, 2023).
tumor (4 papers, 2008 to 2025). "The qRT-PCR analysis of 20 pairs of BC and adjacent non-tumor tissues showed that the expression of PDGFRB, COMP, GREM1, and FRRS1 was higher in BC tissues than in non-tumor tissues." (PMID 36895470, 2023). "RT–PCR and immunohistochemistry on independent cases validated prognostic significance for several genes including RECQL4, FRRS1, CFH and MET – whose combined expression carried greater prognostic value than tumour grade – and cmet and TRKB proteins." (PMID 18382428, 2008).
cancer (1 paper, 2025). A tumor composed of atypical neoplastic, often pleomorphic cells that invade other tissues. "FRRS1 upregulation, involved in iron metabolism, is increasingly recognized as a critical vulnerability in cancer cells, with elevated iron levels supporting rapid proliferation and DNA synthesis." (PMID 41009348, 2025).
FRRS1 also shares sentences with these, for which no sentence is quoted: glioma (1 paper); prostate carcinoma (1).